PRC1 (protein regulator of cytokinesis 1)
Diseases named in the same sentence as PRC1 in open-access papers (continued):
Sharing a sentence is not in itself a finding about the gene and the disease.
tumor (145 papers, 2012 to 2025). "Su26 discovered that the protein regulator of cytokinesis 1 (PRC1) mediated the recruitment of tumor-associated macrophages and regulatory cells (Tregs), which facilitated immunosuppression and angiogenesis in double-negative prostate cancer." (PMID 37752167, 2023). "E3 SUMO‐protein ligase CBX4 (CBX4), a key component of polycomb‐repressive complexes 1 (PRC1), has been reported to regulate a variety of genes implicated in tumor growth, metastasis, and angiogenesis." (PMID 37691307, 2023). "Research has shown that the protein regulator of cytokinesis 1 (PRC1) is associated with the mitotic process of tumor cells and is highly expressed in various carcinomas." (PMID 36744262, 2023). "For the pathways distribution from the KEGG database (c2.cp.kegg.v7.0), ASPM, CENPF, and PRC1 shared three important tumor-associated terms (KEGG_CELL_CYCLE, KEGG_OOCYTE_MEIOSIS, and KEGG_SPLICEOSOME) in the top five significant pathways." (PMID 33946043, 2021). "Here, we demonstrate that UM progression is driven by loss of PRC1 in a subpopulation of tumor cells, leading to transcriptional de-repression of PRC1-target genes and mitotic chromosome segregation errors." (PMID 34518527, 2021). "It has been implicated in promotion of anchorage-independent growth of tumor cells in vitro and clonogenic potential by facilitating ubiquitination activity of protein regulator of cytokinesis 1 (PRC1)." (PMID 33015128, 2020). "PRC1 promotes tumor cell self-renewal and induces the recruitment of M2-like tumor-associated macrophages and regulatory T cells, leading to metastasis initiation of double-negative prostate cancer." (PMID 33101367, 2020). "In the Okayama Lung dataset, the alternation of ADAMTS8, METTL7A, MYH10 and PRC1 were associated with tumor grade, implicating vital roles of these genes in the carcinogenesis or progression of LUAD." (PMID 31333911, 2019). "Loss of the PRC1 component Polyhomeotic (ph) leads to tumour formation characterized by compromised epithelial integrity and cell polarity, neoplastic overgrowth and poor differentiation capacity." (PMID 29357360, 2018). "Loss of the epigenetic Polycomb repressive complex PRC1, which regulates cell identity during normal development, leads to tumour formation in epithelial tissues, supported by aberrant signalling activities." (PMID 29357360, 2018). "Pcl does not regulate proliferation, and thus differs from some PcG members, such as the PRC1 components Posterior sex combs and Suppressor of zeste 2, loss of which causes tumor-like growth in imaginal discs and the optic lobe (H.A. and I.S., unpublished)." (PMID 27381228, 2016). "In addition, RRM2 and PRC1 were associated with some non-tumor diseases such as sclerocystic ovaries and immunoglobulin A glomerulonephritis, whereas SPAG5 was exclusively associated with pregnancy-related diseases." (PMID 39596028, 2024). "Abnormal expression of PRC1, a protein molecule that plays a key role in cell division, has been linked to the proliferation of tumor cells and even normal cells, and was also thought to affect the process of oxidative stress and participate in the Wnt/β-catenin signaling pathway." (PMID 35387129, 2022). "Moreover, a previous study reported that PRC1 enhances the recruitment of regulatory T cells and M2-like tumor-associated macrophages, contributing to the metastasis of double-negative prostate cancer." (PMID 33150086, 2020). "PRC1 is one of the members of the microtubule-associated proteins (MAPs) family that is involved in cytokinesis and its downregulation caused aberrant spindle formation in the central area during the anaphase phase which leads to chromosomal instability and finally tumor evolution." (PMID 41187218, 2025).
tumor (continued). "It was uncovered that PRC1 silencing led to significant suppression on tumor growth, which was also reflected by the smaller tumor size and lighter tumor weight in the PRC1 silencing group." (PMID 40847353, 2025). "Consistent with our expected results, PRC1 expression level was higher in tumor tissues compared with adjacent normal kidney tissues, highlighting the outstanding diagnostic and prognostic performance of PRC1 in ccRCC progression." (PMID 40093809, 2025). "PRC1 was detected in 25% of the B4-treated A549/DDP tumor tissues, while only 10% of the B4 and cisplatin treated tumor tissues was PRC1 positive." (PMID 40355412, 2025). "PRC1 knockdown reduces ccRCC cell proliferation, migration, and colony formation, implicating its role in tumor growth." (PMID 40093809, 2025). "The results indicated that PRC1 presented significant high expression in tumor tissues obtained from both COAD and READ patients." (PMID 40847353, 2025). "Meanwhile, IHC data obtained from HPA database indicated that positive PRC1 expression was higher in tumor tissues than that in normal tissues collected from COAD and READ patients." (PMID 40847353, 2025). "Knockdown of PRC1 in A549 cells using siRNA confirmed its role in neoplasm activity and progression." (PMID 40612866, 2025). "PRC1 dysregulation is reported in various tumors, including hepatocellular carcinoma, breast cancer, and gastric cancer, correlating with high tumor grade, aggressiveness, and poor prognosis." (PMID 40093809, 2025). "Protein regulator of cytokinesis 1 (PRC1) has been proven to be a tumor promoter in CRC and an immune marker." (PMID 40847353, 2025). "Ultimately, PRC1 was the only gene in the CPTAC database that exhibited significantly higher protein levels in tumor tissues compared to paraneoplastic tissues." (PMID 40093809, 2025). "High PRC1 expression confers tumor cell resistance to immune surveillance and enhances self-renewal capacity, promoting the proliferation and metastasis of hepatocellular carcinoma." (PMID 40042761, 2025). "Ultimately, we also analyzed the correlation between PRC1 expression levels and the infiltration of immune cells in the tumor microenvironment." (PMID 40093809, 2025). "We elucidate a novel molecular pathway whereby PRC1 exerts carcinogenic role in tumor immune microenvironment through ICD in CRC." (PMID 40847353, 2025). "Low BAP1 leads to the accumulation of H2A ubiquitination, reinforcing the PRC1-mediated repression of tumor suppressor genes, thus creating a permissive environment for ERG overexpression and tumor progression." (PMID 40136571, 2025). "Firstly, PRC1 exhibits elevated expression in ccRCC relative to non-tumor tissues, a finding corroborated by data from TCGA, GEO, CPTAC, and the NJMU dataset." (PMID 40093809, 2025). "In vitro and in vivo studies showed that knockdown of PRC1 using siRNA or shRNA significantly inhibited tumor growth and proliferation by arresting cells at G2/M and inducing mitotic catastrophe and apoptosis through the caspase 3 pathway." (PMID 40034437, 2025). "Last, our identification of PRC1 as a transcriptional repressor of Drm implicates the Drm–Hyd–Lin–Bowl cascade as an important tumor suppressor pathway that couples this critical epigenetic regulator to tissue growth and tumorigenesis." (PMID 39137945, 2024). "Stable as well as transient reduction of RITA in tumor cell lines, normal cells or MEFs results in an enlarged area of PRC1 staining in mitotic spindles of prometaphase and metaphase cells, and in the central spindle of anaphase cells as well." (PMID 39839673, 2024). "Together, these observations also highlight the importance of core PRC1 subunits as tumor suppressors and guardians of genome stability." (PMID 38888809, 2024). "PCGF2 is also a component of the PRC1 core complex and maintains the transcriptional repression of genes involved in embryogenesis, cell cycle, and tumor suppression." (PMID 35179962, 2022).
tumor (continued). "Consistently, PRC1 was positively correlated with the tumor genomic instability biomarkers, MSI, HRD, and LOH." (PMID 35983074, 2022). "According to the tumor T stage, upregulation of PRC1 was observed in T1, T2, T3, and T4 stage compared with normal tissue." (PMID 35983074, 2022). "In contrast, some subunits of PRC1 have also been reported to have tumor-suppressive roles such as CBX6 and PCGF2 in breast cancer." (PMID 36076977, 2022). "Further experiments have shown that ZFP36 can bind to PRC1 mRNA, thereby downregulating the expression of PRC1, inhibiting tumor growth, and promoting 5-Fu sensitivity." (PMID 34252149, 2021). "ZFP36 was shown to bind to the 3′UTR of PRC1 mRNA, thereby down-regulating PRC1 expression and exerting an anti-tumour effect." (PMID 34328175, 2021). "TRIM37, PRC2, and PRC1 are co-bound to tumor suppressive genes, resulting in their transcriptional silencing and oncogenic function." (PMID 33391428, 2021). "In prostate cancer, for example, BMI1 (PCGF4) binds to the androgen receptor (AR) independently of the PRC1 complex thereby preventing protein degradation, which results in sustained AR signalling promoting tumour growth." (PMID 34316702, 2021). "CBX7 inhibits YAP/TAZ, down-regulates CTGF (adverse prognostic product of tumor) with PRC2 as a member of PRC1, and reduces the phosphorylation level of c-Jun NH2-terminal kinase (JNK)." (PMID 34659360, 2021). "PRC1 is involved in the completion of cytokinesis and is abnormally regulated in a tumor-specific manner." (PMID 33292244, 2020). "Further, PRC1 can promote cell proliferation, migration, and invasion, promote tumor growth and metastasis, increase chemoresistance, and inhibit apoptosis in HCC." (PMID 32213663, 2020). "Consistent with previous studies, our experiments also indicated that PRC1 was obviously higher in tumor tissues compared with normal paracancer tissues." (PMID 33292244, 2020). "Then, an in vivo tumor formation assay was conducted to explore the effects of PRC1 on tumor growth." (PMID 33292244, 2020). "The Bmi1 subunit of PRC1 mediates the repression of tumor suppressors in myeloid progenitors and is required for the inhibition of tumor suppressor genes that is necessary to initiate the self-renewal of CSCs in solid tumors." (PMID 30283976, 2019). "Consistent with the previous studies, our current study suggests that PRC1 was up-regulated in HBV-related HCC tumor tissue, and high PRC1 expression promotes a poor OS and RFS." (PMID 31737106, 2019). "In tumors, CBX family proteins have been shown to endow PRC1 with distinct functions, such as oncogene or tumor suppressor functions." (PMID 30357595, 2019). "It was proposed that PRC1 limits the expression of theseneo-PRC1 genes that are mainly involved in cell proliferation, cell signalingand polarity, thus explaining its tumor suppressor role." (PMID 29995890, 2018). "Alterations in gene expression programs are intrinsic to tumorigenesis, and abrogation of PRC1 function in ph clones will expectedly lead to chromatin changes that support tumour initiation." (PMID 29357360, 2018). "After verifying that the expression behavior of PRC1 was closely related to proliferation and cell cycle in vitro, we continued to explore its effects on tumor growth." (PMID 29752448, 2018). "In agreement with this, blocking JAK/STAT activity suppresses the PRC1 mutant tumor phenotype and in our hands induces the re-establishment of the differentiation program characteristic of eye-antennal imaginal discs." (PMID 29560857, 2018). "The tumor suppressive role of PcG proteins, in particular PRC1 members in Drosophila imaginal discs, has been extensively investigated." (PMID 29560857, 2018). "Although depletion of PRC1 in BJ cells also resulted in an increased fraction of binucleated cells, this effect was less pronounced compared to the tumor cell lines." (PMID 29435157, 2018).
tumor (continued). "Simultaneously, we observed that PRC1 knockdown in OSCC cell lines caused G2/M phase arrest (p < 0.05), inhibited cell proliferation in vitro (p < 0.05) and tumor growth in vivo (p < 0.001)." (PMID 29752448, 2018). "Previous studies have shown that knockdown or knockout of PRC1 is an efficient method of inhibition of tumor growth including breast, bladder and cervical cancers." (PMID 29752448, 2018). "Significantly, non-tumorigenic BJ cells were less sensitive to the inhibition of PRC1 compared to the tumor cell lines." (PMID 29435157, 2018). "We further analyzed data of 336 HCC and 42 non-tumor samples of patients from The Cancer Genome Atlas (TCGA), a significant upregulation of PRC1 in HCC tissues was suggested." (PMID 29748662, 2018). "At 21 days after tumor inoculation, mice harboring tumors with reduced PRC1 expression showed dramatically decreased tumor growth compared to the control groups, as demonstrated by the substantially reduced tumor size and weight." (PMID 28646916, 2017). "The mean tumour weight from PRC1‐depleted cells was less than one‐third of those from scramble control cells after 21‐day growth in vivo." (PMID 28190297, 2017). "When the stable cells were injected into mice subcutaneously, the PRC1‐depleted tumours grew much more slowly than the scramble control tumours did." (PMID 28190297, 2017). "BMI1 (a member of the PRC1) has recently been shown to be involved in tumor progression and metastasis, probably mediating CSC function." (PMID 26517683, 2015). "CBX7 is an essential component of the polycomb repressive complex 1 (PRC1) involved in the control of histone methylation at tumour suppressor loci such as p16." (PMID 24875049, 2014). "PRC1 functions as an inhibitor of transcription during embryogenesis and in neoplastic transformation, as a tumor suppressor." (PMID 25538889, 2014). "The situation in HFs is in stark contrast to the evidence from human tumor cell lines where the PRC1 proteins are typically found in a small number of very prominent nuclear bodies associated with pericentromeric heterochromatin." (PMID 24485159, 2014). "For example, removal of PRC1 components from Drosophila eye imaginal discs leads to increased proliferation and tumor-like phenotypes, possibly via deregulation of the Notch or JAK/STAT signaling pathways." (PMID 24358021, 2013). "Finally, the in vivo experiments demonstrated that silencing of PRC1 restrained tumor growth in CRC animal models." (PMID 40847353, 2025). "The TMA analysis revealed increased levels of CCNY, TET2, and phosphorylated PRC1 in tumor tissues." (PMID 40665337, 2025). "The levels of PRC1 and PLK1 in tumor cells were detected by IHC to explore whether the sensitization effect of B4 for cisplatin was due to the inhibition of PLK1/PRC1 signaling pathway." (PMID 40355412, 2025). "PRC1 has been proven to be a tumor promoter in CRC and an immune cell marker." (PMID 40847353, 2025). "Furthermore, Quantitative real-time PCR experiment of clinical samples revealed significantly higher PRC1 expression levels in ccRCC tumor samples compared with adjacent normal kidney tissues." (PMID 40093809, 2025). "Additionally, PRC1 expression was correlated with the activation of the Wnt/β-catenin pathway, suggesting that PRC1 plays a pivotal role in tumor progression." (PMID 40093809, 2025). "In addition, our work has elucidated the context-dependent oncogenic/tumor-suppressive function of BAP1 and highlighted the potential of therapeutically attenuating PRC1 activity in BAP1-deficient cold tumors." (PMID 39817454, 2025). "Likewise, PH depletion at L2 or early L3 stage induces tumours, suggesting that PRC1 is required throughout development to prevent tumorigenesis." (PMID 38658752, 2024). "The deregulation of PRC1 can promote tumor progression by inducing chromosomal instability, and targeting chromosomal instability could be an effective strategy of early therapeutic intervention in UM." (PMID 38966635, 2024).
tumor (continued). "Interestingly, exosomes derived from human umbilical cord mesenchymal stem cells (hUCMSCs) can transfer miR-139-5p to tumor cells, leading to the suppression of PRC1, a protein involved in tumorigenesis." (PMID 38298209, 2024). "Similar to PRC2, PRC1 also plays dual roles as an oncogenic and tumor suppressor." (PMID 36076977, 2022). "Therefore, our study expands the understanding of PRC1 function and provides an alternative tumor therapy strategy: inhibiting PRC1 by targeting its regulatory kinase, CDK16." (PMID 35449080, 2022). "In addition, PRC1 was positively correlated with the expression of tumor immune checkpoint molecules." (PMID 35983074, 2022). "The correlation between PRC1 and cytokines was analyzed and adjusted for tumor purity." (PMID 35983074, 2022). "The protein regulator of cytokinesis 1 (PRC1) has been shown to exert an oncogenic function by promoting tumor formation, transfer, stemness, and progression of early HCC through the Wnt/β-catenin signaling pathway modulation, and its overexpression has been linked to poor HCC patient survival." (PMID 36118880, 2022). "Thus, deregulation of PRC1 can promote tumor progression by inducing CIN and represents an opportunity for early therapeutic intervention." (PMID 34518527, 2021). "Recently, mutations in the polycomb repressive complex (PRC) pathway were discovered in the BC genome, with PRC2 directing DNA hypermethylation and silencing genes involved in myeloid differentiation and with tumor suppressor function and PRC1 repressing similar and novel tumor suppressors." (PMID 33435150, 2021). "Our findings strongly suggested that PRC1 down-regulation inhibited xenograft-tumor growth in vivo." (PMID 33292244, 2020). "Finally, our findings from xenograft tumor growth assays demonstrated that silencing of PRC1 expression inhibited the weight and volume of the tumor." (PMID 33292244, 2020). "Due to the incomplete follow-up data for 5–10 years, the association between PRC1 expression and clinical features (such as OS, gender, age, size tumor, and so on) has not been investigated in the collected 40 patients." (PMID 33292244, 2020). "Finally, we established xenograft tumor model to investigate the effect of PRC1 on tumor growth in vivo." (PMID 33292244, 2020). "Activation of JAK/STAT and Notch signalling has been reported in tumours lacking a functional Polycomb Repressive Complex 1 (PRC1) due to loss of polyhomeotic (ph), which contribute to their growth." (PMID 29357360, 2018). "To further investigate whether PRC1 knockdown suppresses tumour growth in vivo, we generated stable PRC1 knockdown HGC27 cell population." (PMID 28190297, 2017). "Here, we analyzed whether elevated levels of the polycomb repressor complex 1 (PRC1) components Bmi1 and Ring1b and their catalyzed histone modification H2AK119ub in ADMs and tumor cells, are responsible for the mediation of acinar gene silencing." (PMID 26716510, 2016). "Moreover, H2AK119ub was massively enriched in 3D-ADMs and tumor cells, indicating that PRC1 was catalytically active already in ADM." (PMID 26716510, 2016). "As a result of the interaction between YY1 and RYBP, the role of RYBP cannot be clearly explained, and some studies suggest that RYBP may support tumor progression by stabilizing PRC1 and repressing tumor suppressor genes, and its function seems dependent on the cellular context." (PMID 40867231, 2025). "Notably, PRC1 (but not PRC2) has been shown to function as a tumor suppressor in Drosophila imaginal discs, with its loss of function leading to tissue overgrowth." (PMID 39137945, 2024). "Furthermore, we found associations of tumor related hypermethylation with PRC1- and PRC2-regulated regions, as well as a significant overlap of hypomethylated regions with T-cell–specific and tumor-relevant transcription factor–binding regions and motifs and thymocyte specific enhancers." (PMID 33310759, 2021).